HIF1A (hypoxia inducible factor 1 subunit alpha)
Diseases named in the same sentence as HIF1A in open-access papers (continued):
Sharing a sentence is not in itself a finding about the gene and the disease.
osteomyelitis (6 papers, 2022 to 2026). An acute or chronic inflammation of the bone and its structures due to infection with pyogenic bacteria. "Using LysMCre and the corresponding floxed Hif1afl/fl and Vhlfl/fl alleles, myeloid-lineage conditional knockouts of Hif1a (Hif1afl/fl, LysMCre+/-; Hif1aΔMyeloid) and Vhl (Vhlfl/fl, LysMCre+/-; VhlΔMyeloid) were generated and subjected to S. aureus osteomyelitis." (PMID 36204648, 2022). "Utilizing a murine osteomyelitis model induced by Staphylococcus aureus, we conducted a comprehensive investigation of the in vivo functions and mechanisms of HIF-1α and SETD2 in the development and progression of osteomyelitis." (PMID 38830934, 2024). "Consistent findings were revealed in clinical analysis involving 28 osteomyelitis patients, whose serum HIF-1α mRNA levels were also much higher than those of the 14 healthy controls with matched age, gender, body mass index (BMI), and demographic." (PMID 35852344, 2022). "In a model of endodontic infection resembling osteomyelitis, the inhibition of HIF-1α was followed by a reduction in reactive bone formation." (PMID 35562962, 2022). "In this investigation, we employed two models of S. aureus infection-induced osteomyelitis in order to reveal the roles of HIF-1α and TGF-β1 in its pathogenesis both in vitro and in vivo." (PMID 35852344, 2022). "Our results suggests that hypoxia/HIF-1α/TGF-β1 signaling is involved in osteomyelitis pathogenesis." (PMID 35852344, 2022). "Based on these findings, we hypothesized that SETD2 might regulate the expression of HIF-1α, thereby modulating macrophage glycolysis in osteomyelitis." (PMID 38830934, 2024). "Furthermore, this study reports for the first time that SETD2 suppresses M1 macrophage polarization and glycolysis by regulating HIF-1α via catalysis of H3K36me3 in the context of osteomyelitis." (PMID 38830934, 2024). "Next, we set out to identify the downstream effector of HIF-1α in the osteomyelitis setting." (PMID 35852344, 2022). "This study hereby suggests a novel signaling cascade involving hypoxia/HIF-1α/TGF-β1 in osteomyelitis pathogenesis, which could potentially serve as a target for therapeutic measures." (PMID 35852344, 2022). "Upon S. aureus infection, hypoxia was activated to trigger TGF-β1 upregulation through direct targeting of HRE on TGF-β1 mRNA by HIF-1α, eventually leading to osteomyelitis symptoms in terms of osteogenesis and mineralization deficiencies as well as elevated inflammation." (PMID 35852344, 2022). "Our study has hereby proposed a novel signaling cascade involving hypoxia/HIF-1α/TGF-β1 in osteomyelitis pathogenesis, the components of which could potentially serve as targets for therapeutic measures." (PMID 35852344, 2022). "Currently, it remains unclear whether HIF-1α is activated during osteomyelitis." (PMID 38830934, 2024). "Previous studies have shown that HIF-1α is upregulated in S. aureus-infected MC3T3-E1 cells and osteomyelitis patients." (PMID 39337422, 2024). "Conditional knockout of Hif1a in both the osteoblast and myeloid lineages does not impact bacterial burdens or infection-associated changes in bone architecture, suggesting that Hif1a does not contribute to pathogenesis during S. aureus post-traumatic osteomyelitis." (PMID 36204648, 2022). "Next, to investigate the roles of HIF-1α and TGF-β1 in S. aureus infection-induced osteomyelitis, specific silencing of these two genes was introduced into MC3T3-E1 cells." (PMID 35852344, 2022). "According to these results, HIF-1α and TGF-β1 were upregulated in S. aureus-exposed MC3T3-E1 cells and in osteomyelitis patients." (PMID 35852344, 2022). "To further test the roles of HIF-1α and TGF-β1 in osteomyelitis in vivo, we employed a mouse model of S. aureus infection-induced osteomyelitis." (PMID 35852344, 2022).
osteomyelitis (continued). "Here, have investigated in a similar osteomyelitis mouse model and revealed hypoxia/HIF-1α as the probable upstream activator of TGF-β1, thereby deepening the current understanding of osteomyelitis pathogenesis." (PMID 35852344, 2022). "S. aureus infection increased HIF-1α expression and serum TGF-β1 concentration in a mouse model of osteomyelitis." (PMID 35852344, 2022). "HIF-1α and TGF-β1 are upregulated in MC3T3-E1 cells infected with S. aureus and in osteomyelitis patients." (PMID 35852344, 2022). "However, the inhibition of HIF-1α in osteomyelitis might bring along adverse effects." (PMID 35562962, 2022). "Hypoxia-inducible factor-1α (HIF-1α) and transforming growth factor β1 (TGF-β1) were both upregulated in S. aureus-infected MC3T3-E1 cells and osteomyelitis patients." (PMID 35852344, 2022). "Besides hypoxia/HIF-1α, the results of this study propose TGF-β1 as a potential therapeutic target of osteomyelitis." (PMID 35852344, 2022). "Despite not yet being investigated in osteomyelitis, one can assume that HIF-1α would also be activated due to the consistency of this finding in other infections with human pathogens." (PMID 35562962, 2022). "Overall, these data suggest that conditional deletion of Hif1a or Vhl in myeloid cells does not affect bacterial burdens during osteomyelitis." (PMID 36204648, 2022). "Overall, these studies demonstrate that bone cell Hif1a does not contribute to control of bacterial burdens and pathologic changes in bone architecture during osteomyelitis." (PMID 36204648, 2022). "Combined, the data from CFU enumeration and post-infection weights suggest that conditional knockout of Hif1a or Vhl in osteoblast-lineage cells does not substantially alter bacterial burdens in this model of S. aureus osteomyelitis." (PMID 36204648, 2022). "After confirming that bacterial burdens do not significantly differ during S. aureus osteomyelitis following genetic ablation of Hif1a or Vhl in the myeloid lineage, we next tested the impact of these conditional knockouts on pathologic changes to bone architecture." (PMID 36204648, 2022). "It is possible that HIF-1α plays an important role in bacterial clearance in other models of osteomyelitis or that differences may exist at time points not investigated in this study." (PMID 36204648, 2022). "However, given the data regarding bacterial burdens and microCT findings from these studies, osteoblast- and myeloid-lineage HIF-1α are not essential for control of S. aureus osteomyelitis." (PMID 36204648, 2022).
peripheral arterial disease (6 papers, 2016 to 2026). A disorder of the arteries supplying the upper and lower extremity and the visceral organs. "Our previous work showed that HIF‐1α is increased in muscle sensory nerves of rats with peripheral artery disease (PAD) induced by femoral artery occlusion." (PMID 33356010, 2021). "Interestingly, forced overexpression of HIF-1α has been tested in clinical gene therapy trials for peripheral artery disease and myocardial ischemia, with varying degrees of success, suggesting that temporal control and tissue targeting are critical factors for therapeutic benefit." (PMID 41150799, 2025). "In peripheral artery disease (P.A.D.), gene therapy research has primarily focused on enhancing blood flow and tissue repair rather than directly targeting HIF-1α." (PMID 41150799, 2025).
retinal diseases (6 papers, 2015 to 2023). "While Ref-1 controls a number of TFs that are under redox regulation, three have been found to directly link cancer studies to retinal diseases; HIF-1α, NF-κB and STAT3." (PMID 34322687, 2021). "HIF-1α being a “master switch” for regulating all oxygen-dependent retinal diseases is critical in construction of new therapeutic avenues for treating retractable retinal insults." (PMID 28289375, 2017). "This is the first report on the effect of zeaxanthin on VEGF and HIF-1α levels in cultured RPE cells and suggests that zeaxanthin may have potential value in the prevention and treatment of various retinal diseases associated with vascular leakage and neovascularization." (PMID 25688362, 2015). "We reveal a regulatory axis of HDAC4-AS1/HIF-1α/HDAC4 in RPE cells under hypoxic stress, and provide therapeutic targets for treating retinal diseases." (PMID 34057022, 2021).
retinopathy of prematurity (6 papers, 2015 to 2025). A bilateral retinopathy characterized by neovascularization, scarring, retinal detachment, and eventually blindness. "Stabilization of Hif-1α protected against photoreceptor cell death in pre-clinical models of retinal detachment and retinopathy of prematurity." (PMID 32984302, 2020). "In vivo, compared to the OIR retina, the upregulation of VEGF, HIF-1α, and PlGF in phase II retinopathy of prematurity (ROP) was inhibited by probenecid administration." (PMID 34690760, 2021). "Similar to the etiopathogenesis of retinopathy of prematurity (ROP), induction of hypoxia-inducible factor-1 α (HIF-1α) may be responsible for the production of vascular endothelial growth factor (VEGFA), which is the main cause of retinal neovascularization." (PMID 32848728, 2020).
serous ovarian carcinoma (6 papers, 2008 to 2026). "HIF-1α expression can be a prognostic biological marker in poorly differentiated serous ovarian carcinoma." (PMID 35496046, 2022). "Our report confirms the prognostic value of HIF-1α when restricted to poorly differentiated serous ovarian carcinoma." (PMID 19014607, 2008). "Clearly, additional studies are needed, however, we strongly support determination of HIF-1-α expression by immunohistochemistry in serous ovarian cancer for devising subgroups for individualized treatment regimens." (PMID 19014607, 2008). "Our report confirms the prognostic value of HIF-1α in serous ovarian cancer in a specific, albeit large, subset of patients." (PMID 19014607, 2008). "From our observations, nuclear HIF-1α expression might represent an important biological marker in the evaluation of the prognosis of patients with poorly differentiated serous ovarian carcinoma." (PMID 19014607, 2008). "EGFR activation can drive HIF-1α up-regulation, leading to VEGF gene expression and providing a positive feedback loop in high grade serous ovarian cancer." (PMID 38057816, 2023). "In the subset of 55 poorly differentiated serous ovarian carcinomas the average patients' age was 62.5 and there was no statistical difference between HIF-1α positive and negative patients in regard to age, Ca 125, and complete/incomplete cytoreduction (p > 0.05)." (PMID 19014607, 2008). "HIF-1α expression in serous ovarian carcinoma was not stage dependent." (PMID 19014607, 2008).
spinal cord injury (6 papers, 2021 to 2026). Penetrating and non-penetrating injuries to the spinal cord resulting from traumatic external forces (e.g., WOUNDS, GUNSHOT; WHIPLASH INJURIES; etc.). "It is postulated that HIF‐1α is involved in the regulation of MIF following spinal cord injury (SCI)." (PMID 37334735, 2023).
systemic sclerosis (6 papers, 2017 to 2025). A chronic disorder, possibly autoimmune, marked by excessive production of collagen which results in hardening and thickening of body tissues. "HIF-1α is a key transcription factor in response to chronic hypoxia and participates in fibrotic diseases, such as systemic sclerosis (SSc)." (PMID 36357371, 2022). "Hypoxia inducible factors-1α (HIF-1α), a key transcriptional factor in response to this chronic hypoxia, is involved in fibrotic disease, such as Systemic sclerosis (SSc)." (PMID 28611671, 2017). "The excessive expression of HIF-1α has been detected in the tissues of systemic sclerosis." (PMID 35231032, 2022). "Accumulation of HIF-1α has been identified in persistent pathofibrogenesis and may play a role in progression of systemic sclerosis (SSc), an inflammatory autoimmune disease resulting in abnormal fibroblast activation and fibrosis leading to skin thickening and organ insufficiency." (PMID 40963621, 2025).
thyroid (6 papers, 2017 to 2026). "Thyroiditis results in elevation of the mTOR/HIF-1α/HK2/glycolysis pathway in CD4+ T cells." (PMID 34149615, 2021). "Similarly, in thyroid tumorigenesis, H2O2 produced by NOX4 increases HIF-1α activity, providing a feedback loop to modulate ROS production." (PMID 35008579, 2021). "In the early phases of thyroid oncogenesis, BRAF p.V600E or RET/PTC oncogenes drive the expression of HIF1α, although the concomitant overexpression of c-MYC, belonging to the same signaling pathway, quickly overturns HIF1α regulation by suppressing BGLT3 transcription at its locus." (PMID 41489907, 2026).
thyroid tumor (6 papers, 2013 to 2022). A benign or malignant neoplasm affecting the thyroid gland. "That we now identify S1P as a non-hypoxic regulator of HIF-1α in follicular ML-1 and FTC-133 cells suggests that S1P-induced HIF-1α expression may be involved in thyroid tumor formation and cancer progression." (PMID 23824493, 2013). "Vit-C levels were also shown to be negatively linked to HIF1-α production in thyroid abrasions, and an in vitro investigation found that Vit-C therapy reduced HIF1-α and GLUT-1 production in thyroid tumors." (PMID 35745630, 2022). "To estimate whether vitamin C content in the thyroid relates to activation of hypoxia pathway, the total ascorbate in the samples was compared with the levels of HIF-1α, HIF-2α and hypoxia-induced glucose transporters which up-regulation in thyroid tumors we had previously reported for." (PMID 29084538, 2017).
vitamin D deficiency (6 papers, 2018 to 2024). A nutritional condition produced by a deficiency of VITAMIN D in the diet, insufficient production of vitamin D in the skin, inadequate absorption of vitamin D from the diet, or abnormal conversion of vitamin D to its bioactive metabolites. "The use of vitamin D3 reduced protein expression, transcriptional activity, and target genes of HIF1‐α in various human cancer cells, substantiating the relationship between vitamin D deficiency and hypoxia." (PMID 36746181, 2024).
abdominal aortic aneurysm (5 papers, 2016 to 2023). Enlargement and ballooning of the vessel that supplies arterial blood to the abdomen, pelvis and legs. "Moreover, HIF-1α is a positive regulator of multiple key pathological processes involved in abdominal aortic aneurysm formation, including oxidative stress, MMPs elaboration, SMC apoptosis and vascular inflammation." (PMID 31853217, 2019). "Significant HIF-1α expression could be found at the rupture edge at human abdominal aortic aneurysm (AAA) tissues." (PMID 27363580, 2016).
acute leukemia (5 papers, 2016 to 2025). A clonal (malignant) hematopoietic disorder with an acute onset, affecting the bone marrow and the peripheral blood. "Vitexin induces apoptosis via modulation of HIF-1α/Bcl-2/caspase-3 pathway and potentiates efficacy of daunorubicin, thereby supporting potential as an adjunctive therapeutic in acute leukemia." (PMID 41392176, 2025). "In acute leukemias, however, markers of intracellular hypoxia such as increased pimonidazole adduct staining and HIF-1α stabilization are observed in advanced leukemic bone marrows (BM) despite an increase in BM vasculogenesis." (PMID 32695673, 2020). "Rg3 suppressed angiogenesis in HIF-1α-mediated acute leukemia by inhibiting PI3K and ERK1/2 signal pathways." (PMID 26636541, 2016). "This study aims to explore the bioregulation of simvastatin in acute leukemia cell lines, the expression of miR-19a-3p and HIF-1α level in AML, the molecular mechanism of miR-19a-3p/HIF-1α in simvastatin inhibiting AML, to lay a theoretical foundation for possible clinical application in the future." (PMID 34895042, 2021).
alcoholic fatty liver disease (5 papers, 2017 to 2025). Lipid infiltration of the hepatic parenchymal cells that is due to alcohol abuse. "The multitargeted effects of T4OL—simultaneously reducing inflammation (NF-κB1/IL-6), hypoxia (HIF-1α), and fibrosis (TGF-β1/MMP1)—make it a promising candidate for ALD treatment, particularly in alcoholic-steatohepatitis and early fibrosis stages." (PMID 40572736, 2025). "Alcoholic steatohepatitis and NASH-associated fibrosis and HCC are apparently not a result of HBx stabilization of HIF-1α." (PMID 29799025, 2018). "In alcoholic fatty liver disease MitoQ has been observed to successfully prevent ethanol-induced oxidant-damage and liver steatosis through a mechanism involving ROS/reactive nitrogen species (RNS) scavenging and the suppression of Hypoxia-inducible factor 1-alpha (HIF1α) activation." (PMID 33557229, 2021).
allergic disease (5 papers, 2012 to 2023). An immune response that occurs following re-exposure to an innocuous antigen, and that requires the presence of existing antibodies against that antigen. "HIF-1α activation is required for inflammatory reactions associated with infections and allergies." (PMID 23133644, 2012). "In addition, we explored the therapeutic effect of the synthetic HIF-1α/STAT5 decoy ODN using a mouse model with DNCB/DfE-sensitized AD-like allergy inflammation and a IgE+Ag-treated mast-cell-like cell line." (PMID 37799329, 2023). "RNA-seq results revealed the HIF-1α to be a potential target for the allergic reaction." (PMID 34421593, 2021). "Therefore, HIF‐1α is likely to play a role in AD and the anti‐allergy mechanism of calycosin may relate to it." (PMID 29993193, 2018). "Furthermore inhibition of HIF-1α attenuated OVA-induced AHR and inflammation via VEGF suppression in bronchial epithelium, which is a critical effector molecule in Th2 driven allergic disease in the lung." (PMID 24223970, 2013).
allergic rhinitis (5 papers, 2011 to 2025). Inflammation of the nasal mucous membranes caused by an IgE-mediated response to external allergens. "Consistently, HIF-1a deficiency in dendritic cells attenuated symptoms and inflammatory indicators in allergic rhinitis mice induced with OVA." (PMID 35915851, 2022). "The reported association with allergic rhinitis is consistent with previously published experimental data highlighting the role of HIF-1α in allergic airway pathology." (PMID 34621299, 2021). "However, to our knowledge, the current study is the first to report on the association between SNPs of the HIF1A gene and allergic rhinitis, acute bronchitis and bronchiolitis." (PMID 34621299, 2021). "Interestingly, HIF-1a has been demonstrated to play an imperative role in allergic rhinitis and CRS, highlighting its role as a major therapeutic target of these diseases in the future." (PMID 35915851, 2022). "Our study suggests that MRPL4 and BCAP, key components of the HIF-1α and PI3K/Akt signaling pathways respectively, are two novel candidate genes for atopy and allergic rhinitis." (PMID 21625490, 2011). "Hence the study of MRPL4, BCAP other molecules involved in the HIF-1α and PI3K/Akt signaling pathways might help understand the pathophysiology of allergic rhinitis and other atopic phenotypes." (PMID 21625490, 2011). "Taken together these data suggest that pathway controlling signaling of HIF-1α would interact with molecules in the PI3K signaling pathways which might lead to the development and progression of allergic phenotypes such as atopy and allergic rhinitis." (PMID 21625490, 2011). "Hence the study of polymorphisms in MRPL4, BCAP and other molecules involved in the HIF-1α and PI3K/Akt signaling pathways might help understand how they are regulated and in turn shed light on the pathophysiology of allergic rhinitis and other atopic phenotypes." (PMID 21625490, 2011).